CCL3 (C-C motif chemokine ligand 3)
Diseases named in the same sentence as CCL3 in open-access papers (continued):
Sharing a sentence is not in itself a finding about the gene and the disease.
Arthritis (continued). "Using the flow cytometry-based, predesigned Human Chemokine CBA Kit, we detected higher levels of CCL2, CCL3, CCL4, CCL5, CXCL9, and CXCL10 in arthritis than in CTRL plasma." (PMID 28619088, 2017). "An amino-terminal-modified methionylated form of CCL5 (Met-RANTES) antagonized the binding of CCL3 and CCL5 to their receptors CCR1 and CCR5, respectively, and the blockade inhibited arthritis in AIA rats via the suppression of neutrophil and macrophage migration into the joints." (PMID 36860872, 2023). "For instance, CCL3 KO mice showed milder clinical and histopathological scores in the CAIA model, whereas plt/plt mice, a naturally occurring CCL19 and CCL20 mutant strain, also showed mild arthritis in CIA model." (PMID 36860872, 2023). "MIP-1α/CCL3 and RANTES/CCL5 demonstrated high constitutive expression on macrophages in adjuvant-induced arthritis, which correlated with the expression of CCR2 (MCP-1/CCL2 receptor) by macrophages and was proved to play an important role in maintaining inflammatory changes in the joints." (PMID 36293292, 2022). "Both IL-1β-induced synovitis and intra-articular lavage resulted in transient joint inflammation with elevations in synovial fluid TP, WBC count, and PGE2; however, increases in TNF-α and inflammatory chemokines CCL2, CCL3, CCL5, and CCL11 were predominantly restricted to synovitis joints only." (PMID 33980227, 2021). "CCL3’s role in modulating experimental arthritis has focused upon measuring synovitis and arthritis incidence rather than bone pathology." (PMID 30053130, 2018). "Moreover, improvement or resolution of arthritis in murine models has been seen after treatment with antibodies to macrophage-derived angiogenic chemokines, including IL-8, ENA-78/CXCL5, MIP-1α/CCL3, MCP-1/CCL2, and fractalkine." (PMID 23725043, 2013). "Notably, radiographic bone erosions were detected in the absence of visual signs of arthritis (arthritis score = 0), suggesting the uncoupling effects of anti-CCL3 treatment on bone resorption from inflammation." (PMID 30053130, 2018). "CCL3 inhibition was initiated at a very specific time point when the formation of arthritogenic anti-collagen antibodies was complete and while clinical signs of arthritis were absent." (PMID 30053130, 2018). "The upregulated expression of TNF-α, IL-1α, IL-1β, IL-4R, P-selectin, MIP-1α (CCL3), MCP-1 (CCL2), NOS2 and NOS3 demonstrated in the present study is in agreement with previous observations of the dependency of the rat SCW-induced arthritis model on these mediators." (PMID 15642130, 2005).
asthma (35 papers, 2008 to 2025). "HDM prestimulation increased the release of IL-18, EGF, TWEAK, and M-CSF and decreased CCL3 in SARS-CoV-2-infected HBECs from patients with asthma in comparison to SARS-CoV-2 infection alone." (PMID 37087523, 2023). "CCR3 is one of the most relevant chemokine receptors in asthma, and its ligands are CCL3, CCL5, CCL11, and CCL13." (PMID 35743888, 2022). "The airway epithelium expresses CCL2, CCL3, CCL4, CCL5, CCL11, and CXCL5, which are associated with asthma." (PMID 35743888, 2022). "further analyzed the effect of CCL3 on airway allergic response using the experimental asthma mouse model." (PMID 27829417, 2016). "Previous studies reported that an increased level of CCL3 was observed in BAL fluids from patients with asthma, and that CCL3 evoked local T cell recruitment and induced skin reactions in patients with atopic dermatitis." (PMID 27829417, 2016). "High levels of CCL3/MIP1α promote inflammation and have been proposed to be involved in a broad range of diseases, from asthma to multiple sclerosis." (PMID 25133186, 2014). "In T2-low asthma, macrophages recruitment is also driven by the epithelial release of CCL2 and CCL3, while in obesity-related asthma, leptin activates airway epithelial cells and induces the production of cytokines such as IL-8, further contributing to neutrophil recruitment." (PMID 35456002, 2022). "The chemokines CCL3, CCL4, and CCL5 are all associated with the migration of macrophages and other leukocytes through their binding to CCR1, CCR4, and CCR5, and have been linked with asthma." (PMID 31024538, 2019). "More importantly, serum CCL-3 and CCL-4 were identified as ideal biomarkers for predicting a favorable SNOT-22 score in response to omalizumab in CRSwNP patients with asthma." (PMID 39758936, 2025). "The levels of CCL2, CCL3, and CCL5 in the BALF and CCL11 in plasma were significantly higher in asthma patients than in control subjects." (PMID 35743888, 2022). "On the other hand, 82 genes were found significantly upregulated in the M-MONO group, including CCL3, IL1B, and several MHC class II genes that were enriched in autoimmune disease pathways (such as rheumatoid arthritis and asthma)." (PMID 35133977, 2022). "To ascertain the mechanisms underlying GLCCI1-mediated regulation of the effects of GCs on chemokines, we began by assessing asthma-related pro-inflammatory chemokines (CCL2, CCL3, CCL4, and CCL7) in lung tissues by RT-PCR." (PMID 34504850, 2021). "CD16+ monocytes preferentially express receptors for chemokines such as CCL3 and CCL5; these chemokines are increased in patients with asthma, indicating a potential link between CD16+ monocytes and asthma pathophysiology." (PMID 26658828, 2015). "The sputum inflammatory mediator profiles were distinct with increased TH2 (IL-5, IL-13, and CCL26) and TH1 mediators (CXCL10 and 11) in severe asthma compared with COPD and increased IL-6, CCL2, CCL3, and CCL4 in COPD compared with severe asthma." (PMID 25129678, 2015). "Furthermore, CCL3 (MIP-1α) and CXCL2 (MIP-2) are important mediators in asthma and COPD because they are chemoattractant for monocytes/macrophages and neutrophils." (PMID 32509795, 2020). "In asthma, the reports on CCL3 expression are not univocal, as increased as well as equal and reduced CCL3 levels have been found depending on the patient cohort, investigated sample or cell type." (PMID 32509795, 2020). "CCL-3 and CCL-4 in serum and IgE, CXCL-1, GM-CSF, and IP-10 in nasal secretion may be considered as preferable biomarkers for predicting favorable or ineffective response to omalizumab therapy in patients with refractory CRSwNP comorbid with asthma, based on various clinical indicators." (PMID 39758936, 2025).
periodontitis (33 papers, 2013 to 2025). An acute or chronic inflammatory process that affects the tissues that surround and support the teeth. "Our scRNA-seq analysis revealed that macrophages expressed Ccl2, Ccl9, Cxcl4, and Cxcl6, and neutrophils expressed Ccl3, Ccl4, Ccl6, Cxcl2, and Cxcl3 throughout periodontitis development." (PMID 38015204, 2023). "Although there is a paucity of data on salivary chemokines in periodontitis, 2 studies have indicated that salivary CCL3 (MIP-1α) levels are significantly associated with periodontitis." (PMID 24944840, 2014). "One of the most abundantly expressed chemokine in periodontitis tissues is macrophage inflammatory protein-1α (MIP-1α/CCL3) with its expression localized in the connective tissue subjacent to the pocket epithelium of inflamed gingival tissues." (PMID 24151615, 2013). "Another prospective cohort study found that levels of salivary MIP-1α (CCL3) and IL-1β (among 19 other mediators that were assayed) were both significantly elevated in 7 subjects with localised aggressive periodontitis as compared to 41 individuals who stayed healthy." (PMID 24944840, 2014). "Moreover, the upregulation of inflammatory cytokines such as CCL3 and immune response-related genes such as CD74 and HLA-DPB1 in cluster 5 suggests an enhanced immune response within the periodontal microenvironment as a hallmark of periodontitis-associated inflammation and tissue destruction." (PMID 38731950, 2024). "MIP-1α/CCL3, described as an osteoclast differentiation factor, and RANTES/CCL5, a chemotactic factor for these cells, are found in periodontitis tissues." (PMID 24151615, 2013). "Moreover, other important salivary biomarkers that are increased in periodontitis are metalloproteinase (MMP)-8, MMP-9, and the inflammatory protein of macrophages-1α (MIP-1α or CCL3)." (PMID 35225864, 2022). "CD14+ monocytes secrete a variety of cytokines, including TNF-α, IL-1β, IL-6, IL-8, CCL2, CCL3, and CCL5, compared to CD14− cells from GCF in patients with periodontitis, which suggests that CD14+ monocytes may be a source of CCL5 in GCF and gingival tissue in patients with periodontitis." (PMID 38139161, 2023).
pulmonary fibrosis (31 papers, 2008 to 2025). Chronic progressive interstitial lung disorder characterized by the replacement of the lung tissue by connective tissue, leading to progressive dyspnea, respiratory failure, or right heart failure. "In a murine model of BLM-induced lung fibrosis, the time-dependent increase in CCL3 after a BLM challenge was associated with an increased number of leukocytes and elevated profibrotic factors." (PMID 36830702, 2023). "Notably, the binding of CCL3 to CCR1 has been shown to cause fibroblast aggregation in a bleomycin-induced pulmonary fibrosis model, ultimately leading to fibrosis." (PMID 40396273, 2025). "CCL3 plays a central role in pulmonary fibrosis by controlling inflammation and fibrogenesis through leukocyte recruitment and fibrocyte migration." (PMID 39768150, 2024). "CCL3 plays a dual role in pulmonary fibrosis by regulating inflammation and fibrogenesis through leukocyte recruitment and fibrocyte migration." (PMID 39768150, 2024). "Evasin-1, a tick-derived chemokine-binding protein with a high affinity for CCL3, reduces CCL3 expression and leukocyte recruitment in bleomycin-induced lung fibrosis." (PMID 39768150, 2024). "It was observed that when CCL6 was neutralized in BLM-induced lung fibrosis, the expression levels of CCL3, CXCL1, CXCL2 and IL-1β were significantly reduced, indicating the effects of CCL6 on these chemokines and cytokine (sFigure 6B)." (PMID 36934284, 2023). "For example, an anti-CCL1 monoclonal antibody ameliorated BLM- and hMSC-induced lung fibrosis in mice, and blockade of CCL3 with a monoclonal antibody or a CCL3-binding protein (evasin-1) attenuated PF in BLM mice." (PMID 36830702, 2023). "Further, Ccl-12 and Cxcr-4 that were both shown to be involved in pulmonary fibrosis, Ccl-3 which has been described to be important in systemic sclerosis, and Ccr-2 that is associated with allograft fibrosis, were overexpressed." (PMID 24143891, 2013). "This is in agreement with a recent study implicating CCL3 in the development of bleomycin-induced pulmonary fibrosis in the mouse where CCL3 was shown to regulate the recruitment of TGF-β1-producing macrophages and bone-marrow-derived fibrocytes." (PMID 20161726, 2010). "Indeed, CCL-2 is a chemoattractant for fibrocytes, and CCL-3 has been involved in bleomycin-induced recruitment of bone marrow-derived macrophages and fibrocytes, and the subsequent development of pulmonary fibrosis." (PMID 24885771, 2014). "Together, these results suggest that CCL3 may promote S. japonicum-induced fibrogenesis via a mechanism similar to that proposed for bleomycin-induced pulmonary fibrosis." (PMID 20161726, 2010). "Compared with the number of studies on CCL3, relevant in vivo studies of CCL4 in lung fibrosis are quite limited." (PMID 36830702, 2023). "CCL3 (upregulated by HCMV > 48 fold) has been demonstrated to play a role in dermal and pulmonary fibrosis in a murine sclerodermatous disease model and, recently, CCL3 transcripts were found increased in skin biopsies of SSc patients." (PMID 32899126, 2020). "Previous studies showed elevated levels of CCL2, CCL3, and CCL4 in patients with mustard gas-induced pulmonary fibrosis." (PMID 30867053, 2019). "The selective interaction of chemokine CCL3 with its receptor, CCR1, is also crucial for thoracic radiation-induced pulmonary fibrosis." (PMID 30915142, 2019). "Monocytes also promote fibrosis formation through two critical mechanisms: one is to produce proinflammatory cytokines [IFN-α, MIB-α (CCL3) and MIP-1β (CCL4)] to promote myofibroblast differentiation, and the other way is to serve as progenitor fibrocytes to induce pulmonary fibrosis." (PMID 35572564, 2022). "Aberrant activation of CCL3/CCR1 orchestrated the influx of inflammatory cells to the injured sites and triggered tissue repair mechanisms, thereby exacerbating the insult and driving pulmonary fibrosis." (PMID 30915142, 2019).
pulmonary fibrosis (continued). "We recently observed that bleomycin-induced intrapulmonary macrophage accumulation and subsequent pulmonary fibrosis was attenuated in CCL3-KO and CCR5-KO mice but not in CCR1 KO mice." (PMID 18776949, 2008). "However, the predominant role in the development of pulmonary fibrosis in mice is attributed to Ccl3-Ccr5, as the absence of Ccr1 did not impact disease progression and fibrosis." (PMID 39768150, 2024). "In a recent report, it was discovered that the CCR5 ligands CCL3 (macrophage inflammatory protein (MIP)‐1) and CCL4 (MIP‐1) are both considerably raised in BAL fluid of patients with idiopathic pulmonary fibrosis and have an essential impact in animal models of lung fibrosis." (PMID 37647429, 2023). "In controls with ILD due to other diseases, fewer abnormalities were observed; however; some cytokines/chemokines, such as CCL2 and CCL3, were increased in idiopathic ILD as well as in SSc-associated ILD, indicating an important, but nonspecific contribution of these chemokines in lung fibrosis." (PMID 19615053, 2009).
glioma (29 papers, 2013 to 2025). A benign or malignant brain and spinal cord tumor that arises from glial cells (astrocytes, oligodendrocytes, ependymal cells). "Consistent with the findings in human gliomas, Spp1, Aif1 and Ccl3 mainly expressed in glioma-associated macrophages, hemostatic microglia and activated microglia, respectively." (PMID 38515213, 2024). "In pediatric high-grade gliomas, CCL3 facilitates M2 macrophage infiltration into the tumor microenvironment." (PMID 39953613, 2025). "Pro-inflammatory M1 macrophages secrete CCL3, and higher M1 CCL3 expression has been correlated with better survival in human glioma." (PMID 39794971, 2024). "Chemokines associated with T cell trafficking (CCL3, CCL5, CXCL9, and CXCL10) were all upregulated in KR158B glioma tissue compared to naïve tissue." (PMID 39272914, 2024). "Glioma-associated DEGs AKT2, CCL3, STAT2, VEGFC were up-regulated and HIF1A, KRAS, RET, TGFB2 were down-regulated specifically in the dogs." (PMID 29352201, 2018). "For example, the addition of CCL3 to GM-CSF producing glioma cells nullified the therapeutic effect of GM-CSF." (PMID 24967094, 2013). "HBS-101, a novel midkine inhibitor, reduced optic nerve proliferation, normalized RNFL thickness, and decreased the expression of tumor (Neu4, Gpr17) and TME (Ccl2, Ccl3, Ccl4, Ccl5) genes, supporting its continued development as a targeted therapy for pediatric NF1-associated glioma." (PMID 41497446, 2025). "In addition, glioma conditioned media treatment of microglia resulted in a rapid upregulation of gene expression of several CCR1 ligands including CCL3, CCL5, CCL6 and CCL9." (PMID 36982211, 2023). "Furthermore, we show that mRNA for CCR1 and CCR1 ligands, including CCL3, are strongly upregulated in a microglial cell line treated with glioma conditioned media." (PMID 36982211, 2023). "CCL3 is also highly expressed in glioma, and may promote glioblastoma cell proliferation and migration." (PMID 29033691, 2017). "Although the traditional M1 and M2 classifications are considered to be related to the prognosis of patients with gliomas, recent single-cell sequencing revealed that glioma-associated macrophages can be further classified more precisely, such as AIF1+TAMs, SPP1+TAMs and CCL3+TAMs49." (PMID 40898016, 2025). "In glioma cells, CD133, a cancer stem cell marker, raises the expression of IL-1β and its downstream chemokines, including CCL3, CXCL3, and CXCL5." (PMID 33429364, 2021). "It affects the occurrence and development of glioma by regulating a series of tumor-related genes, such as FEN1, CCL3, PLCB1, NRAS and PIK3s, and activation of apoptosis signaling pathways." (PMID 29033691, 2017). "Overall, this study indicated that PHF20 is a pivotal upstream gene that influences the occurrence and development of glioma by regulating a series of tumor-related genes, like FEN1, CCL3, PLCB1, NRAS and PIK3s, and involved in apoptosis signaling pathways." (PMID 29033691, 2017). "We then performed clustering on the TAM subsets from the 17 cross-grade glioma patients and found three major TAM subsets with distinguished expression of CCL3, AIF1, and SPP1 respectively, the three subsets also share most of the marker genes with the previously identified TAMs in grade 2 glioma." (PMID 38515213, 2024). "The importance of CCR1 in mediating glioma invasion was further underscored by the fact that GL261 conditioned media strongly upregulates CCR1 levels and several CCR1-specific ligands (most prominently CCL3) in MG cells." (PMID 36982211, 2023). "The remaining genes (IL-1α, CXCL7, IL-18RAP, CCL3) have not been well-studied in glioma, with the exception of CCL3, which is shown to improve the response to dendritic cell vaccines of patients with GBM." (PMID 31475119, 2019).